ABCC2 (ATP binding cassette subfamily C member 2)
Diseases named in the same sentence as ABCC2 in open-access papers (continued):
Sharing a sentence is not in itself a finding about the gene and the disease.
sickle cell anemia (2 papers, 2017 to 2024). "The second case, a 43-year-old woman with sickle cell disease who died of fulminant liver failure 56 days after starting DFX, tested homozygous for ABCC2 rs369192412 (g.99781071delG)." (PMID 39508042, 2024).
triple-negative breast carcinoma (2 papers, 2016 to 2021). An invasive breast carcinoma which is negative for expression of estrogen receptor (ER), progesterone receptor (PR), and human epidermal growth factor receptor 2 (HER2). "It was shown that increases in the expression of HAS2, HYAL1-2, VEGF and ABCC2 were related to worse prognosis in patients with triple-negative breast cancer (HR: 1.11, 1.14, 1.24, 1.83 and 1.09 respectively)." (PMID 33572239, 2021). "When the three triple negative breast cancer lines were treated with the IC50 dose of doxorubicin, it caused a greater than 3-fold induction of ABCC2 in MDA-MB-231 and HDQ-P1 cells, and a modest but statistically significant increase in MDA-MB-468 cells." (PMID 27029062, 2016).
Amyloid (1 paper, 2024). "In cortex, the expressions of OAT4, OAT1, OATP4C1, and ABCC2 were lower in CKD3/4 and Amyloid groups compared to control group (FDR<0.1)." (PMID 39729035, 2024).
asthma (1 paper, 2019). "We observed that asthma status is associated with an increase in ABCC2 in both datasets." (PMID 30655622, 2019).
atrial fibrillation (1 paper, 2024). A disorder characterized by an electrocardiographic finding of a supraventricular arrhythmia characterized by the replacement of consistent P waves by rapid oscillations or fibrillatory waves that vary in size, shape and timing and are accompanied by an irregular ventricular response. "Alleles associated with increased risk of atrial fibrillation (rs3903239, GORAB-PRRX1) and biliary disorders (rs2002042, ABCC2) were found to have lower frequency." (PMID 39567526, 2024).
autoimmune disease (1 paper, 2023). A disorder resulting from loss of function or tissue destruction of an organ or multiple organs, arising from humoral or cellular immune responses of the individual to their own tissue constituents. "Previous studies have revealed the influence of various SNPs on the toxicity of MTX in patients with autoimmune diseases, such as MTHFR, MTR, ABCC1, ABCC2, and ABCG2." (PMID 37761008, 2023).
bile duct cancer (1 paper, 2016). "In addition, an association of genetic variation in ABCC2 with susceptibility to bile duct cancer has been pointed out41, which would warrant further investigations for cholangiocarcinoma risk focusing on biliary excretion system as well as hepatic metabolizing system." (PMID 27087417, 2016).
Cholestatic liver disease (1 paper, 2026). "Genetic analysis using next-generation sequencing included a panel of five genes involved in cholestatic liver diseases (ATP8B1, ABCB11, ABCB4, ABCC2 and MYO5B)." (PMID 41797682, 2026).
chorioamnionitis (1 paper, 2018). A morphologic finding indicating inflammation of the fetal sac membranes. "Up-regulation of ABCB9, ABCC2 and ABCF2 mRNA was detected in chorioamnionitis (p<0.05), whereas placental ABCB1 (P-gp; p=0.051) and ABCG2 (breast cancer resistance protein-BCRP) mRNA levels (p=0.055) approached near significant up-regulation." (PMID 29402780, 2018). "ABCB9, ABCC2 and ABCF2 were also up-regulated by chorioamnionitis though very little is known concerning the potential function of these transporters in the placenta." (PMID 29402780, 2018). "Similarly, there was a significant correlation between the severity of chorioamnionitis and the increased expression of ABCB1, ABCC2, ABCF2 and ABCG2." (PMID 29402780, 2018).
coronary heart disease (1 paper, 2022). "In this study, 213 Chinese patients with coronary heart disease were included and the influence of ABCC2 gene polymorphisms (rs717620, rs2273697, and rs3740066), CYP2C19*2, and CYP2C19*3 on clopidogrel response were analyzed." (PMID 36278153, 2022).
depressive disorder (1 paper, 2024). A melancholy feeling of sadness and despair. "Moreover, ABCC2 also regulates the transport of glucocorticoids, which are critical mediators of the stress response and intimately associated with the onset and progression of depressive disorders." (PMID 38874508, 2024).
dysplasia (1 paper, 2015). A usually neoplastic transformation of the cell, associated with altered architectural tissue patterns. "Our study replicates and further corroborates these previous findings by including healthy individuals, and, furthermore, assessed the levels of ABCC2 and ABCG2 in the normal-mild dysplasia-severe dysplasia-carcinoma sequence." (PMID 25793771, 2015).
familial intrahepatic cholestasis (1 paper, 2018). An instance of intrahepatic cholestasis that is caused by an inherited modification of the individual's genome. "Disruption of expression of these transporters is pathologic as evidenced by inherited mutations of ABCB11 and ABCC2 which cause progressive familial intrahepatic cholestasis and Dubin–Johnson disease, respectively." (PMID 29643332, 2018).
generalized epilepsy (1 paper, 2021). Epilepsy that is characterized by generalized seizure types and may have typical interictal and/or ictal EEG findings that accompany generalized seizure types (for example generalized spike-wave). "In particular, ABCC2-24TT or CT+TT genotypes and ABCC2 3972 CT+TT genotypes are associated with drug resistance in patients, especially in generalized epilepsy." (PMID 33804537, 2021).
glioblastoma (1 paper, 2023). The most malignant astrocytic tumor (WHO grade IV). "iPSC induced with U87MG CSCs CM were found to overexpress CSC-specific markers CD133, CD44, ABCG2 and ABCC2, which confirmed these cells as iPSC-derived glioblastoma stem cells (iPSC-GSCs); these markers are more than monolayer U87MG, as observed." (PMID 37509281, 2023).
glioma (1 paper, 2016). A benign or malignant brain and spinal cord tumor that arises from glial cells (astrocytes, oligodendrocytes, ependymal cells). "We investigated levels of multiple drug resistance-related genes in U87 and primary glioma cells, including genes related to drug efflux (ABCB1, ABCC1, ABCC2, ABCC4, ABCG2, ATM), DNA damage repair (MGMT) and stemness (CD133)." (PMID 27486877, 2016).
glomerulonephritis (1 paper, 2014). A renal disorder characterized by damage in the glomeruli. "The relative order of magnitude in transcript expression for glomerulonephritis patients was ABCC2>SLCO1A2>ABCB1 = ABCG2 for SLE and SLCO1A2>ABCC2>ABCB1>ABCG2 for SVV." (PMID 24548980, 2014). "Our studies demonstrated reasonable leukocyte expression of transporter transcripts (ABCC2, ABCB1, ABCG2; 90% of patients and SLCO1A2; 50% of patients) in the blood of glomerulonephritis patients." (PMID 24548980, 2014).
ischemia (1 paper, 2023). A hypoperfusion of the BLOOD through an organ or tissue caused by a PATHOLOGIC CONSTRICTION or obstruction of its BLOOD VESSELS, or an absence of BLOOD CIRCULATION. "Another study showed that Abcc2 mRNA expression in the rat liver tissue was higher in the IR injury group compared with the sham group under the conditions of four-hour reperfusion after ischemia." (PMID 38168520, 2023).
kidney injury (1 paper, 2022). Trauma to the kidney. "Our previous studies demonstrated that JBP485 regulates the expression of OATs and multi-drug resistance-associated protein 2/ABCC2 (MRP2) to attenuate drug-induced kidney injury." (PMID 35754503, 2022).
kidney tumor (1 paper, 2023). "Using IHC data from the Protein atlas database, we observed strong or moderate staining for ACAA2, ACAT1, ASRGL1, and AKR1B10, weak staining for ANGPTL4 and ABCC2 in normal kidney tissues and opposite staining results in kidney tumor samples." (PMID 36829161, 2023).
metastatic tumors (1 paper, 2012). "For instance, resistance of metastatic tumors to the anthracycline doxorubicin (DOX) has been linked to overexpression of ABC transporters ABCB1 (MDR1/P-glycoprotein), ABCC1 (MRP1), ABCC2 (MRP2) and ABCG2 (MXR, BRCP)." (PMID 22791660, 2012).
Nausea (1 paper, 2021). A sensation of unease in the stomach together with an urge to vomit. "The objective for this study was to investigate whether MTX-induced nausea was associated with selected SNPs in candidate genes encoding MTX transporter proteins (SLCO1B1, SLCO1B3, SLC19A1, ABCB1, ABCC2), the MTHFR enzyme (MTHFR) and the 5-HT3-receptor (HTR3A, HTR3B), in children with JIA." (PMID 33794950, 2021).
oral squamous cell carcinoma (1 paper, 2021). "A separate study in oral squamous cell carcinoma also identified significant impairment of drug transporters MRP1 and ABCC2 after ANRIL knockdown, which resulted in increased cisplatin cytotoxicity." (PMID 34681828, 2021).
osteomalacia (1 paper, 2021). Disorder caused by an interruption of the mineralization of organic bone matrix leading to bone softening, bone pain, and weakness. "Our department has analyzed 76 ADV-induced osteomalacia patients, and revealed a higher percentage of the GA genotype at rs3740070 of the ABCC2 gene in osteomalacia patients than in healthy people." (PMID 33995038, 2021).
plaque psoriasis (1 paper, 2021). "Here, we identified the ABCC2 rs717620 genotype as a determinant of methotrexate drug survival in plaque psoriasis in both the univariate analysis using log-rank tests and the multivariate Cox proportional hazards regression." (PMID 34684087, 2021).
psoriasis (1 paper, 2021). An autoimmune condition characterized by red, well-delineated plaques with silvery scales that are usually on the extensor surfaces and scalp. "Our previous study showed an important association between ABCC2 rs717620 genotype and methotrexate efficacy in psoriasis, whereby variant allele carriers were more likely to achieve adequate disease control with methotrexate, possibly due to this increased methotrexate exposure." (PMID 34684087, 2021). "It therefore appears that ABCC2 rs717620 has additional potential as a biomarker of methotrexate treatment in adults with moderate-to-severe psoriasis." (PMID 34684087, 2021).
Sepsis (1 paper, 2023). Sepsis is defined as life-threatening organ dysfunction caused by a dysregulated host response to infection. "In addition, Abcc2 is reported to be associated with sepsis." (PMID 37255592, 2023).
skin reaction (1 paper, 2023). "In patients receiving sorafenib, SNPs in ATP-binding cassette sub-family C member 2 (ABCC2) and human leukocyte antigens A (HLA-A) were associated with severe skin reactions, whereas VEGF-R2 was associated with PFS and OS." (PMID 37370844, 2023).
squamous cell carcinoma (1 paper, 2017). A carcinoma arising from squamous epithelial cells. "qRT-PCR tests revealed that gemcitabine triggered a significant increase in ABCB1 and ABCC2 expression both in adeno and squamous cell carcinoma tissues while paclitaxel and doxorubicin differentially initiated drug transporter transcription." (PMID 28340578, 2017).
toxicity (1 paper, 2014). The degree to which an agent can damage an organism. "ABCC2 rs2273697 was also associated with decreased liver toxicity (p = 0.028; OR = 0.23; 95% CI = 0.06−0.85)." (PMID 24991206, 2014).
urothelial carcinoma of the urinary bladder (1 paper, 2021). "For patients diagnosed with urothelial carcinoma of the urinary bladder, upon DDP treatment, DDP‐induced CCAAT/enhancer‐binding protein delta expression activated ABCB1 and ABCC2, and the high expression of ABCB1 and ABCC2 resulted in a decline in the effect of DDP." (PMID 32815556, 2021).
Wilson disease (1 paper, 2020). A very rare inherited multisystemic disease presenting non-specific neurological, hepatic, psychiatric or osseo-muscular manifestations due to excessive copper deposition in the body. "In the present study we report the clinical case of five siblings who were found to carry the ABCC2 c.3972C > T SNP; among them, three were affected by Wilson disease and two brothers with Wilson disease also developed PLCs during their life." (PMID 33208122, 2020). "Here we report the clinical case of five siblings carrying the ABCC2 c.3972C > T SNP; three of them were affected by Wilson disease and two brothers with Wilson disease also developed PLCs." (PMID 33208122, 2020).
cancer (74 papers, 2008 to 2026). A tumor composed of atypical neoplastic, often pleomorphic cells that invade other tissues. "ABCC2 is known to be implicated in chemotherapy resistance, but it is also thought to contribute to cancer aggressiveness beyond its potential role in treatment resistance." (PMID 38456605, 2024). "ABCC2 is a multidrug resistance-associated protein in cancer and associated with resistance to cisplatin." (PMID 37589509, 2023). "We found that the TSIRS was negatively correlated with cancer stemness (mRNAsi) and positively correlated with the expression of multi-drug resistance associated protein (ABCC2, ABCC3, ABCC6 and ABCC10)." (PMID 36467413, 2022). "ABCC2 polymorphisms are widely reported to be associated with chemotherapeutic drug response in cancer treatment." (PMID 36185621, 2022). "Multidrug resistance‐associated protein 2 (ABCC2), an ATP‐binding cassette multidrug resistance transporter, was found to be overexpressed in various human cancers." (PMID 32815556, 2021). "Several studies showed that single nucleotide polymorphisms (SNPs) of the ABCC2 gene are associated with altered distribution, metabolism and elimination of a plethora of drugs in several types of cancer." (PMID 32327612, 2020). "In a cohort-based association study involving 111 cancer patients, genotyping of ABCC1/MRP1, ABCC2/MRP2, and ABCC4/MRP4 was conducted using real-time PCR with TaqMan probes." (PMID 41751467, 2026). "The analysis revealed significant variations in ABCC2 expression between tumor and adjacent normal tissues across multiple cancer types." (PMID 40429829, 2025). "We evaluated the expression patterns of ABCC2 across tumor and normal tissues using the TCGA pan-cancer dataset." (PMID 40429829, 2025). "There is also evidence showing that the elimination of ABCC2 can retain the drug inside the cell, improving chemotherapeutic sensitivity of cancer cells." (PMID 39309428, 2024). "Previous studies have reported that TGFBR1 and ABCC2 were the direct targets of miR-665 in other cancers." (PMID 35034552, 2022). "Another target of miR-665, ABCC2, is a member of the ATP-binding cassette transporter superfamily and is often involved in multidrug resistance in various kinds of cancers." (PMID 35034552, 2022). "Consistently, the protein levels of pSTAT3, SOX2, CDA, and ABCC2 in cancer cells were increased after incubation with miR-660-3p-silenced CAFs, while miR-660-3p overexpression in CAFs reversed this effect." (PMID 35045883, 2022). "Consistently, the protein levels of pSTAT3, SOX2, CDA, and ABCC2 in cancer cells were decreased after silencing CAV1 in CAFs." (PMID 35045883, 2022). "Collectively, these results indicate that the reduced expression of ABCC2 is likely to restore DDP sensitivity in DDP‐resistant NSCLC cancer cells." (PMID 32815556, 2021). "It has a protective effect on the body, and at the same time, the expression of ABCC2 is also closely related to the effect of chemotherapy on malignant tumours." (PMID 32815556, 2021). "ABCB1, ABCB4, ABCG2, and ABCC2 are well-described markers of drug resistance development in many cancers." (PMID 31991882, 2020). "In previous reports, CD44 expression has been linked to chemoresistance based on ABC transporter overexpression including ABCB1 and ABCC2 in various tumors especially in the cancer stem cell compartment." (PMID 29371972, 2017). "Other important ABC transporters implicated in MDR of cancers include MRP1 and MRP2 (MDR1-related protein 1 and MDR-related protein 2) encoded by ABCC1 and ABCC2 genes, respectively." (PMID 27756418, 2016). "In consequence, it is comprehensible that patients with high expression of ABCG2 and ABCC2 (and thus potentially high cancer-stem cell burden) exhibit poor survival." (PMID 25275603, 2014). "ABCC2, an ATP-binding cassette multidrug resistance transporter, is found to be expressed in a variety of human cancers." (PMID 18834541, 2008).
cancer (continued). "Although UAs are MDR1 substrates, they do not affect the expression of ABCB1, ABCC1, and ABCC2 genes in certain cancer cells, suggesting a lower risk of developing resistance and highlighting their strong anticancer potential." (PMID 40806689, 2025). "It was described earlier that CUDC-907 could restore cisplatin sensitivity in cancer cells by decreasing ABCC2 expression, resulting in the accumulation of platinum drugs in the cells and increased cell cycle arrest." (PMID 41148814, 2025). "ATP-binding cassette subfamily C member 2 (ABCC2) can be induced by oxidative stress in various cancer cells, enhancing its capacity for GSH efflux, thereby promoting lipid ROS accumulation and increasing cellular sensitivity to oxidative stress and ferroptosis." (PMID 40861444, 2025). "ABCC2 (MRP2) and ABCG2 (BCRP) are among the most important drug transporters that determine the pharmacokinetics of many drugs and whose overexpression is associated with cancer chemoresistance." (PMID 38612927, 2024). "However, several articles have reported that high expression of ABCC2 is a marker of better prognosis in several cancer types, which is counterintuitive because one would assume that ABCC2‐mediated drug efflux would be beneficial to tumour cell growth." (PMID 39095325, 2024). "We hypothesized that blocking ABCC2 would enhance the cancer response to the current first‐line therapy (VEGF TKI, e.g., sunitinib)." (PMID 29896907, 2018). "Studies have found that one of the mechanisms of MDR is the overexpression of ATP-binding cassette (ABC) superfamily of transporters in cancer cells, such as P-glycoprotein (P-gp/ABCB1), MDR-associated protein 2 (MRP2/ABCC2), and breast cancer resistance protein (BCRP/ABCG2)." (PMID 29334793, 2018). "The results indicate that ABCC2 as a drug transporter might play a role in the sunitinib medication influence of the treated cancer cells." (PMID 29896907, 2018). "The results of the present study suggest that high ABCC2 activity in cancer tissue even before drug treatment could contribute to inherent multidrug resistance, i.e. that the patient does not respond to initial chemotherapy." (PMID 25793771, 2015). "Furthermore, it had been reported that after treatment with RNAi targeting ABCC2, decreased nuclear membranous ABCC2 protein expression in the CDDP-resistant cancer cell lines was observed." (PMID 20628484, 2010). "Moreover, the impact of ABCC2 on tumour prognosis may extend beyond cancer cells themselves, potentially enhancing the anti‐tumour ability of immune cells through glutathione efflux." (PMID 39095325, 2024). "Currently, it is recognized that the main role in multi-drug resistance of cancer cells in vitro is played by ABCB1 (P-gp), ABCC1 (MRP1), ABCC2 (MRP2), ABCC4 (MRP4), ABCG2 (BCRP) and lung resistance protein (LRP)." (PMID 36613834, 2022). "ABC transporters including ABCB1, ABCC1, ABCC2, and ABCG2 are involved in the reduction of chemosensitivity in cancer cells." (PMID 34066059, 2021). "ABC family members including ABCB1, ABCC1, ABCC2, ABCC3, and ABCG2 were critical for CDDP resistance of cancer cells." (PMID 33754002, 2021). "The development of cancer chemoresistance is upregulated by several ABC transporters including ABCB1, ABCC1, ABCC2, and ABCG2." (PMID 34066059, 2021). "Expression of the major ABC transporters, including ABCA1, ABCB1, ABCC1, ABCC2, ABCC3 and ABCG2, was assessed in chemoresistant cancer cells transfected with si-ERRγ." (PMID 32206097, 2020). "A “multitarget multiribozyme” (MTMR) containing three trans-acting hammerhead ribozymes that, after autocatalytic self-activation, cleave the transcripts of the ABC transporter genes ABCB1, ABCC2, and ABCG2 tested positive in several cancer cell models." (PMID 29401721, 2018).